Y_RNA (Y RNA )
Gene: Miscellaneous RNA gene on chromosome 17 (4,186,326 to 4,186,424, forward strand). Ensembl gene ENSG00000251812.
Homologues: Orthologues: chimpanzee Y_RNA (98% identical). Paralogues in human: Y_RNA (81% identical), RNY3P14 (80% identical), Y_RNA (80% identical), Y_RNA (79% identical), RNY3 (78% identical), Y_RNA (78% identical), RNY3P1 (77% identical), Y_RNA (77% identical), Y_RNA (76% identical), Y_RNA (75% identical), RNY3P11 (74% identical), RNY3P16 (74% identical), and 88 more.